KRT19 (keratin 19)
Diseases named in the same sentence as KRT19 in open-access papers (continued):
Sharing a sentence is not in itself a finding about the gene and the disease.
craniopharyngioma (2 papers, 2024). A benign, partly cystic, epithelial tumor of the sellar region, presumably derived from Rathke pouch epithelium. "Keratins, such as KRT19 and KRT17, were consistently expressed, suggesting their potential role as common markers for craniopharyngioma tumor cells." (PMID 39483146, 2024).
disc degeneration (2 papers, 2021 to 2025). "During intervertebral disc degeneration, notochord‐derived nucleus pulposus cells progressively transdifferentiate into Krt19+ chondrocyte‐like cells (CLCs) and Krt19− CLCs, which are eventually replaced by Krt19− CLCs from non‐notochordal Gli1+ progenitors." (PMID 40977276, 2025). "Among which, KRT19 and COL6A2 were considered as important degeneration markers in the previous studies, while the SNPs and mutations of COL11A2 are also linked to disc degeneration." (PMID 33536009, 2021). "However, their conclusion was based on only two CLC‐resident discs, which may did not have Krt19− C‐CLCs and D‐CLCs, since these two CLC subtypes most likely form at later stages of disc degeneration." (PMID 40977276, 2025).
influenza (2 papers, 2024 to 2025). An acute viral infection of the respiratory tract, occurring in isolated cases, in epidemics, or in pandemics; it is caused by serologically different strains of viruses (influenzaviruses) designated A, B, and C, has a 3-day incubation period, and usually lasts for 3 to 10 days. "Two proteins associated with influenza (LIF, KRT19 (which was also related to HHVs)) and one protein associated with skin and subcutaneous infections (CTNNA3) remained statistically significant at P < 0.05 after FDR correction." (PMID 39143319, 2024).
lobular breast carcinoma (2 papers, 2018 to 2022). "Immunohistochemistry showed cytokeratin-19 and oestrogen receptor, but not tireoglobulin, e-cadherin or cytokeratin-7, thereby confirming metastases from a lobular breast carcinoma." (PMID 29409458, 2018). "Immunohistochemistry revealed cytokeratin-19 and oestrogen receptor, but not tireoglobulin, e-cadherin or cytokeratin-7, thereby suggesting metastases from a lobular breast carcinoma." (PMID 29409458, 2018).
metastatic colorectal cancer (2 papers, 2016 to 2023). "The aim of current study was to investigate expression of Cytokeratin 19 (CK19), Cytokeratin 20 (CK20) and Guanylyl Cyclase C (GCC) mRNA in peripheral blood of non- metastatic colorectal cancer patients which may result into introducing of an early detection test." (PMID 27386436, 2016).
oral epithelial dysplasia (2 papers, 2024 to 2025). "Interestingly, Epi1.2 cells are found in the epithelial basement membrane, and the expression of KRT19, a marker for Epi1.2 cells, gradually increased in oral epithelial dysplasia (OED), OSCC, and malignant OSF, associated with changes in matrix stiffness." (PMID 38650025, 2024). "The progressive increase in cytokeratin 19 (CK19) expression from normal mucosa to oral epithelial dysplasia and through the various histological grades of OSCC highlights its potential role in oral carcinogenesis." (PMID 40746926, 2025).
prostate tumor (2 papers, 2017 to 2022). "In particular, we found primarily overexpression of CTNNB1, CDH1, SMAD2, SMAD3, TCF3, LEF1 in younger patients and overexpression of SNAI1 and underexpression of KRT5, KRT19, OCLN, CDH2 and MUC1 which clearly indicates different characteristics of prostate tumor in younger vs older patients." (PMID 29206234, 2017).
psoriasis (2 papers, 2021 to 2024). An autoimmune condition characterized by red, well-delineated plaques with silvery scales that are usually on the extensor surfaces and scalp. "In serological assessments, elevated levels of cytokeratin 19 fragment (CYFRA21-1) were noted in both MASLD and lean MASLD groups, implying a potential synergistic role between psoriasis and MASLD." (PMID 38813379, 2024). "Using ELISA, we analyzed the expression of KRT19 and HSPD1 in lesional skin as well as the PBMC of qPCR/ELISA psoriasis patients and healthy volunteers." (PMID 34575702, 2021).
salivary gland tumors (2 papers, 2015). "Keeping in mind the complexity and heterogeneity of presentations of salivary gland tumors and to effectively diagnose our cases, we used fine needle aspiration cytology and immunohistochemistry markers such as S100, Cytokeratin 19, EMA (epithelial membrane antigen), and DOG 1 stain." (PMID 26783481, 2015).
Skeletal myopathy (2 papers, 2021 to 2025). "In a mouse model, knockdown of KRT19 caused skeletal myopathy via mitochondrial and sarcolemmal reorganization." (PMID 33442422, 2021). "This is of interest, as the absence of Krt19 in mice has been demonstrated to cause skeletal myopathy with mitochondrial and sarcolemmal reorganization." (PMID 41165044, 2025).
teratoma (2 papers, 2015 to 2024). A non-seminomatous germ cell tumor characterized by the presence of various tissues which correspond to the different germinal layers (endoderm, mesoderm, and ectoderm). "This robust validation step underscored the potential of AGR2 and KRT19 as reliable biomarkers for differentiating teratoma from necrosis in clinical practice." (PMID 38396829, 2024). "Secondly, it paves the way for the development of targeted therapies specifically aimed at teratoma, exploiting the unique vulnerabilities exposed by AGR2 and KRT19 overexpression." (PMID 38396829, 2024).
thoracic tumors (2 papers, 2019 to 2023). "We also evaluated the KRT19 expression rate in different types of primary thoracic tumours by IHC and OSNA." (PMID 31331335, 2019).
bronchogenic carcinoma (1 paper, 2015). A lung carcinoma arising from the bronchial epithelium. "The chest X-ray of this patient was normal; however, the causative factor, bronchogenic carcinoma, was diagnosis unanticipated by the hint of elevated tumor maker cytokeratin-19-fragment (CYFRA21-1) and neuron-specific enolase (NSE)." (PMID 26064126, 2015). "However, scope occurred again and the elevated tumor makers cytokeratin-19-fragment and neuron-specific enolase revealed the bronchogenic carcinoma, which was confirmed by enhanced CT examination." (PMID 26064126, 2015).
dermatitis (1 paper, 2023). An inflammatory process affecting the skin. "When samples obtained at the time of dermatitis were compared with 12-week samples from controls, IgM antibody against cytokeratin 19 antigen was higher in patients with dermatitis." (PMID 38152395, 2023). "Only the IgM antibody against cytokeratin 19 showed an increase from baseline to the time of toxicity among dermatitis cases (p=0.014, FDR=0.93) and was elevated during dermatitis events compared with the 12-week control samples (p=0.016, FDR=0.85)." (PMID 38152395, 2023).
dry eye (1 paper, 2017). "Accordingly, we show that SS-associated dry eye-mediated denervation of the chronically inflamed cornea is accompanied by increased proliferation of corneal epithelial basal cells and altered differentiation of KRT19-positive progenitor cells to their KRT12-positive corneal lineage." (PMID 28926640, 2017).
esophageal tumors (1 paper, 2015). "Immunohistochemical staining specific for human cytokeratin 19 (CK19) on the PDX tissue confirmed a human origin of the epithelial cell compartment, with better staining in the moderately- to well-differentiated models compared to the poorly differentiated esophageal tumors EAC023 and EAC027." (PMID 25884700, 2015).
Granuloma (1 paper, 2025). A compact, organized collection of mature mononuclear phagocytes, which may be but is not necessarily accompanied by accessory features such as necrosis. "Compared to patients with granulomas, cases with increased cytokeratin 19 (31.1% vs 21.0%) and CEA (17.5% vs 4.5%) were all more common in patients with PLCs (each p < 0.05)." (PMID 40684047, 2025).
HIV-1 infection (1 paper, 2018). The type species of lentivirus and the etiologic agent of acquired immunodeficiency syndrome (AIDS). "HIV-1 infection of CER and VAG cells was determined by dual intracellular staining for HIV-1 Gag and epithelial marker cytokeratin 19 (CK19) proteins after exposure to HIV-1 (IIIB or Bal)–HTLV-1-coinfected primary CD4+ T cells (two left panels) or T cell lines." (PMID 29624497, 2018).
hypercoagulability (1 paper, 2021). "The results of the logistic regression analysis showed that clinical stage (P < 0.05), cytokeratin 19 fragment (Cyfra211) (P < 0.05), and the platelet-to-lymphocyte ratio (PLR) (P < 0.05) were positively correlated with hypercoagulability." (PMID 33854597, 2021).
keloid (1 paper, 2022). An irregularly shaped, elevated mark on the skin caused by deposits of excessive amounts of collagen during wound healing. "Most keratins were downregulated in keloids, including KRT10, KRT14, KRT15, KRT19, KRT1, KRT77, and KRT5." (PMID 35435317, 2022).
lung disease (1 paper, 2024). "Direct interactors with the CFTR protein, including SNAP23, KRT19, PPP2R1A, and PPP2R4 proteins, were also identified as lung disease modifiers in a longitudinal study." (PMID 40225935, 2024).
malignant mesothelioma (1 paper, 2013). A malignant neoplasm of the pleura or peritoneum, arising from mesothelial cells. "The cytokeratin-19/CEA ratio is a useful diagnostic marker for malignant mesothelioma." (PMID 23516439, 2013).
meningioma (1 paper, 2012). A generally slow growing tumor attached to the dura mater. "Glial fibrillary acidic protein, CD99, CD34, S-100 protein, neuron specific enolase, neurofilament, cytokeratin, cytokeratin 19, and Bcl-2 were negative in MA and meningioma area." (PMID 23198201, 2012).
mesenchymal tumors (1 paper, 2010). "Five genes were significantly differentially expressed in chordoma tumors compared with three control groups (nonchordoma mesenchymal tumors, normal tissues, and IVD): T, CD24, COL2A1, CA3, and KRT19." (PMID 21253487, 2010).
metastatic prostate carcinoma (1 paper, 2024). A carcinoma that arises from the prostate gland and has spread to other anatomic sites. "Notably, the metastatic prostate cancer patients demonstrated a greater expression of all six genes assessed, including AR, androgen receptor variant 7 (AR-V7), PSA, PSMA, EpCAM and cytokeratin 19 (KRT-19)." (PMID 38607014, 2024).
nasopharyngeal carcinoma (1 paper, 2025). A carcinoma arising from the nasopharyngeal epithelium. "A total of 24 nasopharyngeal carcinoma (NPC) cases and 22 benign cases were evaluated for cytokeratin 8/18 (CK8/18) and cytokeratin 19 (CK19) immunohistochemical expression." (PMID 41008664, 2025).
paraganglioma (1 paper, 2025). A benign or malignant neoplasm arising from paraganglia located along the sympathetic or parasympathetic nerves. "Furthermore, immunohistochemistry (IHC) in this case revealed cytokeratin 19 (CK19) expression, a finding not previously documented in veterinary paragangliomas, highlighting the potential diagnostic and biological significance of immunohistochemical profiling in these tumors." (PMID 40948633, 2025).
preeclampsia (1 paper, 2016). Preeclampsia is a hypertensive disorder of pregnancy that is characterized by new-onset hypertension with proteinuria presenting after 20 weeks of gestation, and depending on mild or severe forms may initially present with severe headache, visual disturbances, and hyperreflexia. "Although CYFRA 21–1 (a fragment of Cytokeratin 19) is considered a promising biomarker for diagnosing preeclampsia, little is known regarding the levels of CYFRA 21–1 during pregnancy." (PMID 27809797, 2016).
prostate adenocarcinoma (1 paper, 2022). "Therefore, we next assessed the correlation of KRT15 and KRT19 expression with overall survival in the Metastatic Prostate Adenocarcinoma (SU2C/PCF Dream Team) patient cohort." (PMID 36033462, 2022).
retinoblastoma (1 paper, 2025). A malignant tumor that originates in the nuclear layer of the retina. "Among the most upregulated genes were KRT5, KRT19, LCN2, SLP1 and S100A9, while GNAT1, PDE6G, WIF1, FRZB, and RHO were among the top downregulated genes in retinoblastoma." (PMID 40395327, 2025).
salmonellosis (1 paper, 2014). Infections with bacteria of the genus salmonella. "After 10 days of infection, an early time point used to assess establishment of salmonellosis, histopathologic analysis showed evidence of mild pancreatic edema, but no cytokeratin 19-positive epithelial metaplasia or significant fibrosis." (PMID 24717768, 2014).
scleroderma (1 paper, 2022). Scleroderma is a rare autoimmune connective tissue disorder characterized by abnormal hardening of the skin and, sometimes, other organs. "The atrophic KRT19+ sweat glands in scleroderma mice recovered to a normal level in the organoid treatment group than in the untreated group." (PMID 35315234, 2022).
supraglottic cancer (1 paper, 2014). "Zhao examined primary tumours and 182 neck lymph nodes from twenty patients using dissection of supraglottic cancer with immunohistochemical staining (i.e., anti-cytokeratin 19 and H&E staining)." (PMID 25365429, 2014).
urinary tract infection (1 paper, 2024). "In the control group, the majority of the top 20 DEGs were associated with the epithelial cells, including epithelial barrier‐related genes (CLDN4, KRT19, and KRT18), and SLPI, a key gene reported to be localized to bladder epithelial cells and protect against urinary tract infection in mouse model." (PMID 38414668, 2024).
Uterine leiomyoma (1 paper, 2012). The presence of a leiomyoma of the uterus. "In uterine leiomyoma, the majority of the 30 CpG dinucleotides in the KRT19 promoter were consistently methylated." (PMID 22428009, 2012). "To validate that DNA methylation leads to gene silencing of the tumor suppressor genes KLF11, DLEC1, and KRT19, we assessed mRNA levels in vivo using real-time RT-PCR in uterine leiomyoma and matched myometrial tissues." (PMID 22428009, 2012).
tumor (981 papers, 1998 to 2026). "The intermediate filament keratin 19 (KRT19) has been linked to tumour progression and chemoresistance in various cancers." (PMID 41714116, 2026). "In vitro, we assessed the effects of KRT19 on tumour-associated mechanisms, including proliferation, migration, adhesion, and spheroid formation." (PMID 41714116, 2026). "In the study herein, we found that tumor cell-intrinsic KRT19 deficiency results in cell cycle arrest in G1 phase and the accumulation of SA-β-gal, thus directly suppressing NSCLC progression ultimately." (PMID 41345704, 2025). "Conversely, CD52 and KRT19 were identified as predictive biomarkers linked to the tumour microenvironment (TME) of BC,39, 42, 43 whereas genetic variations in IL7R dramatically raised the susceptibility to BC in Chinese Han women." (PMID 39098994, 2024). "Consistent with this, the analysis of differentially expressed genes (DEGs) in tumor spatial clusters gexC02 and gexC03 revealed upregulation of Epcam, Krt19 and Anhak, markers commonly associated with epithelial cells." (PMID 39605490, 2024). "Among the CAF-induced PNET liver metastasis–related genes, AGR2 and cytokeratin 19 (CK19) were particularly analyzed because of their high fold changes and potential association with tumor aggressiveness." (PMID 38341509, 2024). "Regarding human Pheo/PGLs, transcriptome and methylome data revealed that high levels of promoter methylation of of Keratin19 (KRT19) were able to distinguish SDHB-mutated tumours from all other Pheo/PGL tumours." (PMID 37033265, 2023). "Cytokeratin-19 (CK-19) expression is associated with increased tumor invasion, a higher rate of lymph node metastasis, and poorer postoperative prognosis in HCC." (PMID 37500964, 2023). "Carcinoembryonic antigen(CEA), CA199, NSE, squamous cell carcinoma-associated antigen(SCC), CA-125, keratin 19 fragment, and ferritin were elevated in some patients in the tumour marker assay." (PMID 36587212, 2022). "Such a switch in expression markers associated with MYC resembles the expression of Epcam and Krt19 in Myc-HRasG12V, whereas they are undetectable in Myc-p53shRNA tumours." (PMID 36433941, 2022). "Chosen cutoff for cytokeratin 19 fragment antigen (CYFRA 21-1) as a tumor biomarker considerably influences its diagnostic and prognostic usefulness." (PMID 37360615, 2020). "Serological biomarkers such as carcinoembryonic antigen (CEA) and cytokeratin 19 soluble fragment (CYFRA21-1) are tumor associated antigens (TAAs) commonly used for NSCLC, but their utilities in early stage tumors and prognosis of surgical outcome are limited." (PMID 33585249, 2020). "For instance, keratin family proteins such as keratin 19 indicate high risk of tumor metastasis, invasion, and poor prognosis in HCC patients." (PMID 30345303, 2018). "For example, KRT19 expression has been reported to be associated with poor tumor differentiation and aggressive tumor behavior in hepatocellular carcinoma." (PMID 29100303, 2017). "Subsequently, multi-marker RT-PCR analysis was used to detect tumor-associated transcripts, including KRT19, MUC1, EpCAM, CEACAM5, and BIRC5." (PMID 28626429, 2017). "In human malignant tumor, KRT19 was associated with the proliferation and invasive behavior of tumor cells." (PMID 27833076, 2016). "The authors conclude that downregulation of KRT19 is highly associated with tumor progression in NB and metastasis in localized primary NB and that low expression of ERBB3 is also associated with progression of NB." (PMID 23135478, 2013). "Supporting this, our results demonstrated that low expression of KRT19 was significantly associated with high tumor stages, MYCN amplification and an unfavorable outcome in NB." (PMID 23135478, 2013). "Previous work linked high KRT19 expression in PDAC tumours to poorer survival outcomes." (PMID 40244011, 2025).